TASOR2 (transcription activation suppressor family member 2)
Description:
Core component of the HUSH2 complex, a multiprotein complex that mediates epigenetic repression of interferon-stimulated genes. TASOR2 is recruited to interferon-stimulated genes by IRF2, leading to transcriptional silencing by the HUSH2 complex via a H3K9me3-independent mechanism. Within the HUSH2 complex, TASOR2 acts as the central scaffold, which recruits MPHOSPH8 and PPHLN1.
Synonyms: C10orf18; FAM208B; KIAA2006; FLJ20360; bA318E3.2
Tractability: PROTAC: UniProt records ubiquitination sites on it; ubiquitination databases record sites on it.
Gene: Protein-coding gene on chromosome 10 (5,684,731 to 5,763,779, forward strand). Ensembl gene ENSG00000108021.
Subcellular location: Nucleus; Chromosome
Subcellular location (Human Protein Atlas): Nucleoplasm; Cytosol
Gene Ontology:
Molecular function: protein binding; protein-macromolecule adaptor activity
Biological process: negative regulation of gene expression, epigenetic; negative regulation of type I interferon production
Cellular component: chromatin; chromosome; cytosol; HUSH2 complex; nucleoplasm; nucleus
Genetic constraint (gnomAD): Loss-of-function variants: 72 observed, 189.18 expected, observed/expected ratio (o/e) 0.38, 90% interval 0.31 to 0.46. The upper end of that interval is the gene's LOEUF score, 0.46, which puts it in group 2 of 6, group 1 being the genes least tolerant of losing a copy. Missense variants: 2,701 observed, 2,878 expected, observed/expected ratio (o/e) 0.94, 90% interval 0.91 to 0.97. Synonymous variants: 1,067 observed, 1,072.5 expected, observed/expected ratio (o/e) 0.99, 90% interval 0.94 to 1.05.
Homologues: Orthologues: chimpanzee TASOR2 (98% identical), macaque TASOR2 (92% identical), rabbit TASOR2 (67% identical), dog TASOR2 (65% identical), rat Tasor2 (58% identical), guinea pig TASOR2 (58% identical), mouse Tasor2 (58% identical), pig TASOR2 (55% identical), tropical clawed frog tasor2 (19% identical), zebrafish tasor2 (16% identical), Caenorhabditis elegans T11G6.5 (7% identical). Paralogues in human: TASOR (11% identical).
Diseases named in the same sentence as TASOR2 in open-access papers:
TASOR2 is named in the same sentence as 5 diseases in open-access papers, as found by Europe PMC text mining. Sharing a sentence is not in itself a finding about the gene and the disease. The quoted sentences say what the papers report.
liver cancer (1 paper, 2026). An epithelial or non-epithelial malignant neoplasm that arises from the liver. "According to the Human Protein Atlas (HPA) database, TASOR2 protein expression is elevated in liver cancer and is associated with poorer patient prognosis." (PMID 40824344, 2026).
tumor (1 paper, 2025). "Among these 13, TASOR2 pS1025 and WDR75 pS782 also exhibited significant differences between tumor stages (stage 1 versus others)." (PMID 39793886, 2025).
TASOR2 also shares sentences with these, for which no sentence is quoted: melanoma (2 papers); infection (1); nevus (1).